RETN (resistin)
Diseases named in the same sentence as RETN in open-access papers (continued):
Sharing a sentence is not in itself a finding about the gene and the disease.
metabolic disorders (64 papers, 2004 to 2026). "Various metabolic disease-associated factors other than adiponectin have been reported to affect psoriatic skin phenotypes, such as leptin, chemerin, resistin, and free fatty acids." (PMID 37646025, 2023). "In humans, resistin levels are linked to the metabolic and cardiovascular parameters in cases of metabolic disorders." (PMID 37958823, 2023). "Resistin, a 12.5 kDa polypeptide encoded by the human RETN gene, is still being explored for its potential role as a therapeutic and diagnostic target in several metabolic diseases." (PMID 36686437, 2022). "Gene polymorphism has an important influence on RETN gene expression level, and the increased level of resistin encoded in RETN will lead to metabolic disorder, especially lipid metabolism." (PMID 32143662, 2020). "In this extensive preliminary study in the field, we investigated the long-term effects of maternal resistin on the predisposition of offspring to develop hypothalamic neuroinflammation and subsequent metabolic disorders." (PMID 30845245, 2019). "However, in humans, the association between serum resistin levels and metabolic diseases remains under debate." (PMID 35909571, 2022). "However, it has been reported that increased serum resistin levels have been observed in overweight and obese women, which may lead to metabolic disorders, and it may be associated with minor inflammation." (PMID 33182462, 2020). "Therefore, we speculated that these SNPs may reduce the occurrence of metabolic disorder by inducing a lower level of resistin, ultimately reducing the risk of steroid-induced ONFH." (PMID 32143662, 2020). "Experimental results from cardiomyocytes isolated from diabetic rat hearts suggest that Ca2+ dyshomeostasis and altered Ca2+/ATPase (Serca2) activity are key mechanisms driving the upregulation of resistin expression in this metabolic disorder." (PMID 40283140, 2025). "Numerous adipokines, including adiponectin, leptin, and resistin, are secreted by adipose cells and can result in metabolic disorders and systemic inflammation." (PMID 40941124, 2025). "Adipocytokines, particularly resistin, leptin, and adiponectin, play a crucial role in the onset of obesity and related metabolic diseases." (PMID 38756259, 2024). "The dysregulation of adipocytokines, such as resistin, leptin, and especially adiponectin, plays a pivotal role in the pathophysiology of metabolic diseases." (PMID 38756259, 2024). "Elderly MHO population who eat a MedDiet and practice regularly PA are capable to modulate their production of inflammatory cytokines (CRP, IL-6, TNFa) and adipokines profile (adiponectin, resistin), preventing other metabolic disorders." (PMID 35679338, 2022). "Excess adipose tissue increases the production of pro-inflammatory factors such as leptin, tumor necrosis factor-α, interleukin-6, and resistin which contribute to the development of various metabolic diseases." (PMID 35287586, 2022). "Since its discovery, resistin has attracted considerable interest because of its broad range of physiological and pathological roles in several metabolic diseases." (PMID 36686437, 2022). "It is worth mentioning that the contribution of resistin to metabolic disorders is partly due to inflammation." (PMID 33182462, 2020). "Our results clearly show a positive correlation between resistin plasma levels and clinical parameters of metabolic disease." (PMID 28413567, 2017). "Leptin (gene: LEP), adiponectin (gene: ADIPOQ), and resistin (gene: RETN) are candidate adipokines for investigation of metabolic diseases, as all three are involved in regulation of metabolism, appetite, and insulin sensitivity." (PMID 28413567, 2017). "Pro-inflammatory factors for metabolic disorders such as serum insulin, leptin, and resistin were positively correlated with serum stearic acid and γ-linolenic acid simultaneously." (PMID 28317846, 2017).
metabolic disorders (continued). "Accumulating data indicate that resistin, initially described as a rodent adipokine, is predominantly macrophage-derived in humans and thought to link between inflammation, metabolic diseases and possibly tumorigenesis." (PMID 24465803, 2014). "An investigation of resistin in OSA will therefore provide a better understanding of the complex interrelation between metabolic disorders, inflammation and cardiovascular involvement." (PMID 23497617, 2013). "The aim of this study was to propose a novel adiponectin-resistin (AR) index by taking into account both adiponectin and resistin levels to povide a better indicator of the metabolic homeostasis and metabolic disorders." (PMID 21251282, 2011). "A syntenic gene exists in humans, but is expressed at higher levels in monocytes and macrophages than in adipocytes, raising questions about the relationship between resistin and human metabolic disease." (PMID 15578112, 2004). "Elevated levels of leptin and resistin may decrease inflammatory response and metabolic disorders, indicating how periodontal treatment helps regulate systemic metabolism." (PMID 41244040, 2025). "WC significantly decreased adiponectin expression and increased resistin expression, suggesting that it may induce metabolic disorders through the dysregulation of adipokine expression." (PMID 36814270, 2023). "Therefore, resistin has been suggested as an important modulator and predictor of metabolic diseases." (PMID 35241098, 2022). "Increased leptin and resistin levels result in immune cell infiltration into the adipose tissue through the increase of vascular permeability, which subsequently elevates oxidative stress and inflammatory responses thereby leading to metabolic disorder." (PMID 33643424, 2021). "Resistin is a novel adipocytokine with potential implications in metabolic diseases." (PMID 34257810, 2021). "Some studies have demonstrated that elevated levels of resistin lead to metabolic disorders, which are associated with diabetes, non-insulin dependent, acquired systemic lipodystrophy, rheumatoid arthritis, etc.." (PMID 32143662, 2020). "In fact, we have anticipated that using HFD will exacerbate the difference between CC and CR offspring and determine whether offspring born to dams treated with resistin are prone to inflammation and metabolic disorders." (PMID 30845245, 2019). "The aim of this study was to determine the relationship between PPAR gamma-2 (Pro12Ala, C1431T) and ADRB3 (Trp64Arg) polymorphisms and serum adipocytokines (adiponectin, visfatin, and resistin) and metabolic disorders in 176 postmenopausal women with increased body mass (BMI ≥ 25 kg m−2)." (PMID 27246401, 2016). "Thus, a novel adiponectin-resistin (AR) index was proposed by taking into account both adiponectin and resistin levels to povide a better indicator of the metabolic homeostasis and metabolic disorders." (PMID 21251282, 2011). "Taking the findings together, it may be speculated that the integration of adiponectin and resistin in a novel unified index would be better reflected metabolic homeostasis and metabolic disorders." (PMID 21251282, 2011). "Furthermore, elucidating the role of additional miRNAs in resistin-mediated neuroinflammation may reveal broader regulatory networks that contribute to hypothalamic dysfunction in metabolic disease." (PMID 40759954, 2025). "In addition, WC significantly reduced adiponectin's expression and increased resistin's expression, suggesting that it may induce metabolic disorders through the dysregulation of adipokine expression." (PMID 36814270, 2023). "Adiponectin, resistin, and GLP-1 are influential in metabolic disorders, thus these findings introduce the concept that biliary signaling may modulate insulin resistance and other metabolic diseases associated with NAFLD." (PMID 34440841, 2021). "Therefore, resistin impairment of insulin Akt/eNOS pathway may be an important convergence point linking CV and metabolic diseases." (PMID 30416448, 2018).
metabolic disorders (continued). "Moreover, in obese individuals, visceral adipose expansion leads to the release of high levels of leptin, resistin, TNF-α, and IL-6, and low levels of adiponectin, which promote inflammation and metabolic disorders." (PMID 40095937, 2025). "There was a positive correlation between resistin plasma levels and a negative correlation between RETN DNA methylation and offspring clinical markers of metabolic disease." (PMID 28413567, 2017). "However, a pattern of increased serum resistin levels in metabolic diseases has not previously been reported." (PMID 38662716, 2024). "It has been supposed that resistin might sustain the chronic low‐grade inflammation characterizing the metabolic disorders, but clear evidence is lacking." (PMID 34129696, 2021). "However, the mechanism and importance of increased resistin levels in human metabolic disease are not known." (PMID 15578112, 2004). "This suggests that resistin may act through TLR-4 and not CAP1 during Nb infection, and the importance of CAP1 in resistin-mediated effects may be more significant in metabolic disorders." (PMID 25568944, 2015).
infection (41 papers, 2009 to 2025). The state of being infected such as from the introduction of a foreign agent such as serum, vaccine, antigenic substance or organism. "All infected animals experienced transient weight loss within the first 28 days of infection, but also became hypertriglyceridemic and had up to 10-fold increases in adipocytokines such as resistin and plasminogen activator inhibitor 1 (PAI-1)." (PMID 28085952, 2017). "These associations may highlight a difference between chronic inflammation (for example, mediated by factors such as resistin during T2D) and acute inflammation (for example, during an infection), which is strongly associated with high CRP levels." (PMID 37697054, 2023). "Taken together, our findings suggest that human resistin expression is an innate response to multiple helminths, where it promotes monocyte recruitment and a type 1 proinflammatory cytokine environment, leading to impaired helminth clearance and exacerbated infection-associated inflammation." (PMID 25568944, 2015). "Interactions at the strain level confirmed that only E. coli GMB10 induced significantly higher levels of resistin at 2 h post-infection (p = 0.0051)." (PMID 38672079, 2024). "In this study, we constructed an in vitro cell co-culture system to mimic the in vivo infection process of H. parasuis and investigated the effects of resistin released by PAMs on endothelial integrity." (PMID 36694280, 2023). "The higher pathogen susceptibility of the xcp1 than the lines with XCP1 expressed indicates the function of XCP1 in resisting pathogen infection." (PMID 37542077, 2023). "Remarkably, these changes in blood glucose, insulin and resistin levels persisted long after the infection had resolved (up to 20 weeks post-infection)." (PMID 32409640, 2020). "While our approach lacks the complexity of receptor-targeted studies or transgenic rodent models, the medical literature is still ambiguous regarding the fundamental immune cell-based response to resistin following an acute infection." (PMID 31147868, 2019). "C-reactive protein (CRP), resistin and P-selectin are serological inflammatory markers that rise during the acute stages of infection." (PMID 31856765, 2019). "Employing transgenic mice in which the human resistin gene was inserted, we show that human resistin is induced by infection with the helminth Nippostrongylus brasiliensis, where it promotes excessive inflammation and impedes parasite killing." (PMID 25568944, 2015). "We show that expression of human resistin in mice recruits inflammatory monocytes to the site of infection, promotes type 1 inflammation, and is correlated with increased STH and filarial nematode burden in humans." (PMID 25568944, 2015). "We identified three previously reported biomarkers of infection (neutrophil gelatinase-associated lipocalin (NGAL), granulysin and resistin) and measured gene expression using quantitative real-time PCR." (PMID 22559298, 2012). "In the case of resistin, it would be expected that adipose tissue stores are being mobilized as part of the host response to infection, which includes a high fever typical of infection with HP-PRRSV." (PMID 23110781, 2012). "RETN, identified as an adipokine in 2001, is minimally expressed in healthy individuals, but its level significantly increases upon activation of inflammatory mediators following infection or injury." (PMID 40416430, 2025). "ELISA analysis of resistin was performed on samples obtained at 2, 4 and 6 h post-infection." (PMID 38672079, 2024). "Resistin, IL-6, and myoglobin were all positively correlated with each other in fatal infection." (PMID 37598150, 2023). "However, further studies are necessary to assess the effects of resistin signaling on lung immune function during infection." (PMID 35273609, 2022). "TLR4 and CAP1 are expressed on human alveolar macrophages and type 2 alveolar cells, indicating that resistin could play a role in the lung immune response during infection." (PMID 35273609, 2022).
infection (continued). "We assessed whether bacterial killing capacity was altered based on the ability of these myeloid cells to interact together in the presence of resistin and infection." (PMID 31147868, 2019). "The association of resistin with the amount of albuminuria suggests that the level of plasma resistin is not only influenced by renal clearance but could have some role in the pathogenesis of AKI during PUUV infection." (PMID 30517161, 2018). "Moreover, in the present study, the expression of resistin showed a more tremendous increase in the lean mice than the DIO mice after infection." (PMID 30398974, 2018). "To evaluate whether resistin levels has any correlation with the severity of infection, we categorised the subjects into three groups before starting the ATT." (PMID 26448186, 2015). "In humans, increased resistin expression could be predictive of impaired immunity to helminths or exacerbated inflammation following infection." (PMID 25568944, 2015). "It is possible that the resistin-mediated effects on proinflammatory cytokines operate independently of regulatory mechanisms such as regulatory T cells and IL-10 that also contribute to chronicity of infection." (PMID 25568944, 2015). "In accordance with these reports, we found significantly higher resistin levels in SP, but not in MO, compared to healthy BD supporting the hypothesis that in humans resistin is predominantly a component of the systemic inflammatory response to infection." (PMID 20825686, 2010). "Our results indicate that resistin secreted by PAMs reduces claudin-5 and occludin expression in co-cultured PAECs and increases the permeability of monolayer PAECs, implying that resistin plays an important role in maintaining endothelial integrity during pathogen infection." (PMID 36694280, 2023). "In the porcine model of pulmonary infection with Actinobacillus pleuropneumoniae, the expression of resistin was significantly up-regulated in the porcine lung and hilar lymph nodes, indicating that resistin may play a role in the anti-infection immune response of lung." (PMID 34220862, 2021). "Additionally, our studies of the transgenic mouse model and STH-infected children have provided a useful framework for longitudinal studies to examine whether high resistin expression leads to an increased likelihood of infection with STH." (PMID 25568944, 2015). "In addition to infection-induced resistin expression in the small intestine, we examined if systemic hResistin expression could be predictive of higher worm burden." (PMID 25568944, 2015). "Neutrophilia, low MHCII expression by monocytes, and elevated plasma Resistin, IL-6, myoglobin, and VCAM-1 correlated with fatal infections." (PMID 37598150, 2023). "However, the role of resistin in pathogen infections remains unclear." (PMID 36694280, 2023). "Before infection with E. coli, TNF-α, IL-6, resistin, and leptin contents of the DIO group were significantly higher (p<0.05) than those of the lean group." (PMID 31085802, 2019). "After infection, when compared with the lean group, the contents of TNF-α, IL-1β, IL-6, IL-8, resistin, and leptin in the lean-E." (PMID 31085802, 2019). "Also a negative association was found between infection intensity and resistin levels." (PMID 31856765, 2019). "Based on our results, the DIO mice showed higher MDA contents, GSH-Px activity, and adipocytokine (leptin, resistin, and IL-6) levels than the lean mice, indicating that DIO mice suffered from high oxidative stress levels before infection." (PMID 30250258, 2018). "Before infection with E. coli, the DIO groups had significantly higher contents of IL-6, leptin, and resistin but lower content of IL-8 compared with the lean groups (p < 0.05)." (PMID 30250258, 2018). "In the present study, the pulmonary resistin level was down-regulated in the DIO mice, which was one marker of mild infection status, as well as a delayed inflammatory response." (PMID 30250258, 2018).
infection (continued). "The resistin contents showed a completely different tendency between the lean groups and the DIO groups after infection." (PMID 30250258, 2018). "IL-6, resistin, MIP-1α and MIP-3α were identified during a cytokine microarray of whole blood factors induced by more than 3-fold following E. coli K12, S. epidermidis 1457 or S. aureus SH1000 infection compared to control." (PMID 38672079, 2024). "At the genera level, both Escherichia and Staphylococcus induced significantly high levels of resistin at 2 and 6 h post-infection compared with the control (p < 0.0001) but not significantly different from each other." (PMID 38672079, 2024). "However, it is noteworthy that HFD-fed IAV-infected animals showed lower levels of blood glucose and resistin than HFD-fed mock-treated mice, as was observed at 7 dpi and 20 weeks post-infection under standard diet conditions." (PMID 32409640, 2020). "There was a significant positive association between P-selectin and infection intensity (r = 0.172; p = 0.002) while resistin and CRP did not have a significant association with infection intensity." (PMID 31856765, 2019). "The levels of plasma adipokines (resistin, leptin, adiponectin), and other markers of inflammation (leukocytes, plasma IL-6, CRP) in the acute phase of Puumala hantavirus infection compared to the recovery phase and one year after the infection." (PMID 30517161, 2018). "There was no visible and significant trend of resistin levels during the course of infection in both compartments." (PMID 28428684, 2017). "Our study now shows that resistin is elevated in states of critical illness, even without evident infection." (PMID 19545363, 2009). "However, it is not clear if resistin levels were induced by the high levels of proinflammatory cytokines which are known to be induced upon infection with the DENV and by dengue NS1, or if high resistin levels also contributed to the elevation of these cytokines." (PMID 37676889, 2023). "However, the function of human resistin in infection has not been defined." (PMID 25568944, 2015).
renal disease (8 papers, 2008 to 2023). "Nevertheless, we cannot conclude that resistin is a marker of renal dysfunction because in the subgroup of renal disease activity, the statistical significance of the correlations between resistin and serum creatinine or eGFR were lost." (PMID 33133605, 2020). "The literature on the subject mostly includes studies on resistin in patients with kidney disease." (PMID 36978817, 2023). "Additionally, resistin levels are associated with inflammation and renal disease in SLE, even though a clear difference was not noted between patients and controls." (PMID 34242326, 2021).